TRABD2B (TraB domain containing 2B)
Description:
Metalloprotease that acts as a negative regulator of the Wnt signaling pathway by mediating the cleavage of the 8 N-terminal residues of a subset of Wnt proteins. Following cleavage, Wnt proteins become oxidized and form large disulfide-bond oligomers, leading to their inactivation. Able to cleave WNT3A, WNT5, but not WNT11.
Synonyms: TIKI2
Tractability: Antibody: UniProt places it where antibodies can reach, with high confidence; its Gene Ontology location is reachable by antibodies, with high confidence; UniProt predicts a signal peptide or a membrane-spanning region; the Human Protein Atlas places it where antibodies can reach.
Gene: Protein-coding gene on chromosome 1 (47,760,528 to 47,997,385, reverse strand). Ensembl gene ENSG00000269113.
Subcellular location: Cell membrane; Membrane raft
Subcellular location (Human Protein Atlas): Plasma membrane; Nucleoplasm
Gene Ontology:
Molecular function: metalloendopeptidase activity; protein binding; Wnt-protein binding; endopeptidase activity
Biological process: negative regulation of Wnt signaling pathway; positive regulation of protein-containing complex assembly; proteolysis
Cellular component: organelle membrane; plasma membrane; plasma membrane raft; membrane raft
Genetic constraint (gnomAD): Loss-of-function variants: 13 observed, 29.11 expected, observed/expected ratio (o/e) 0.45, 90% interval 0.29 to 0.71. The upper end of that interval is the gene's LOEUF score, 0.71, which puts it in group 2 of 6, group 1 being the genes least tolerant of losing a copy. Missense variants: 440 observed, 502.15 expected, observed/expected ratio (o/e) 0.88, 90% interval 0.81 to 0.95. Synonymous variants: 210 observed, 206.27 expected, observed/expected ratio (o/e) 1.02, 90% interval 0.91 to 1.14.
Homologues: Orthologues: chimpanzee TRABD2B (99% identical), macaque TRABD2B (98% identical), mouse Trabd2b (90% identical), pig TRABD2B (90% identical), rat Trabd2b (90% identical), rabbit TRABD2B (84% identical), dog TRABD2B (77% identical), tropical clawed frog trabd2b (65% identical), guinea pig TRABD2B (55% identical). Paralogues in human: TRABD2A (57% identical).
Diseases named in the same sentence as TRABD2B in open-access papers:
TRABD2B is named in the same sentence as 6 diseases in open-access papers, as found by Europe PMC text mining. Sharing a sentence is not in itself a finding about the gene and the disease. The quoted sentences say what the papers report.
renal cell carcinoma (2 papers, 2016 to 2023). "Among the poor prognosis-related genes, TRABD2B (also known as TIKI2), IL17F, and GALNTL6 were reported to be related to the oncogenesis of renal cell carcinoma, cutaneous T-cell lymphoma, and thyroid carcinoma, respectively." (PMID 36816541, 2023).
TRABD2B also shares sentences with these, for which no sentence is quoted: osteosarcoma (2 papers); cutaneous T-cell lymphoma (1); hypertriglyceridemia (1); thyroid carcinoma (1); tumor (1).